HNRNPA2B1 (heterogeneous nuclear ribonucleoprotein A2/B1)
Diseases named in the same sentence as HNRNPA2B1 in open-access papers (continued):
Sharing a sentence is not in itself a finding about the gene and the disease.
breast carcinoma (continued). "In addition, breast cancer tamoxifen‐resistant LCC9 cells exhibited highly expressed HNRNPA2B1." (PMID 36162823, 2023). "However, the role of HNRNPA2B1 in the regulation of miRNAs appears to be complex in breast cancer." (PMID 34108450, 2021). "CONCLUSION: Together, our findings reveal a novel ferroptosis-sEVs-mitophagy axis, in which hnRNPA2B1-mediated sEVs ULK1 delivery enhances mitophagy and reprograms macrophage polarization, ultimately restraining breast cancer migration." (PMID 41588464, 2026). "The expression level of HNRNPA2B1 was negatively correlated with immunoinhibitors, immunostimulators, and MHC molecules expressions in breast cancer." (PMID 37671941, 2023). "Taken together, our results suggest that NQO1-AS overexpression in highly metastatic breast cancer cells decouples NQO1 from the broader HNRNPC regulon, enabling NQO1 upregulation via a stabilizing interaction with HNRNPA2B1." (PMID 37169843, 2023). "In this study, the U87MG (glioma), MCF-7 (breast cancer), HepG2 (human liver cancer), and MDA-MB-231 (TNBC) cells were studied to determine the expression level of hnRNPA2B1." (PMID 36015303, 2022). "Among all the RBPs (HNRNPU, HNRNPK, RBM5, HNRNPLL, HNRNPH1, HNRNPM, HNRNPA2B1) screened, only SRSF7 (also known as 9G8) was substantially upregulated in hypoxia-treated breast cancer cells." (PMID 34362878, 2021). "Among them, the expression of RBM15, VIRMA, HNRNPA2B1, and YTHDF1/2/3 were significantly upregulated, but METTL3, METTL14, METTL16, WTAP, FTO, YTHDC1, and EIF3A had lower expression in breast cancer compared to normal samples." (PMID 34804948, 2021). "With the increase of malignancy of breast cancer, the expression level of several m6A RNA methylation regulators, such as FTO, HNRNPA2B1 YTHDC1, IGF2BP1, IGF2BP2 and IGF2BP3, decreased or increased." (PMID 34141492, 2021). "Five out of the six splicing factors have been shown before to be overexpressed in breast cancer: HNRNPA1, HNRNPA2B1, HNRNPK, PTBP1 and SRSF6." (PMID 32756364, 2020). "By comparing tumor and normal samples, we found that six proteins were differentially expressed in breast cancer significantly (P < 0.001), including EIF3A, HNRNPA2B1, HNRNPC, RBMX, YTHDF1, YTHDF2." (PMID 33585234, 2020). "We further clarified the subcellular localization of HNRNPA2B1 by immunofluorescence assay using glioma GL261 cells and breast cancer MDA-MB-231 cells, which showed that HNRNPA2B1 was expressed predominantly in the nucleus and to a lesser extent in the cytoplasm." (PMID 39268079, 2024). "We analyzed the differences in HNRNPA2B1 expression between the immunohistochemical results of 30 normal and 40 breast cancers." (PMID 37671941, 2023). "HNRNPA2B1 can interact with DGCR8 to promote miRNA maturation; however, HNRNPA2B1 can inhibit miR-222, miR-29b-3p, and miR-29a-3p expression and affect the levels of m6A-modified miRNAs, leading to endocrine resistance in breast cancer cells." (PMID 38102645, 2023). "In summary, these results suggest that HNRNPA2B1 may act as an oncogenic factor in NSCLC; however, its specific role in breast cancer remains unclear and further research is needed in this direction." (PMID 34108450, 2021). "That is, HNRNPA2B1 regulates the STAT3 and ERK1/2 signalling pathways in breast cancers." (PMID 34044876, 2021). "Consistent with our results, HNRNPA2B1 has been reported to act as an oncogene in breast cancer, pancreatic cancer, lung cancer, hepatocellular carcinoma, and cervical cancer, while METTL14 functions as a suppressor gene in glioma and breast cancer." (PMID 32582536, 2020). "Moreover, qPCR assays demonstrated that exosomes from hnRNPA2B1 KD breast cancer cells inhibited the expression of the osteoblast differentiation marker genes ALPL, OCN and OSX, an effect that was reversed by exosomes from hnRNPA2B1 KD breast cancer cells transfected with miR-6881-3p mimics." (PMID 38448424, 2024).
breast carcinoma (continued). "Analyses of the Molecular Taxonomy of Breast Cancer International Consortium (METABRIC) and TCGA-BRCA datasets showed a positive correlation between HNRNPA2B1 and NQO1 expression, and, in the case of the TCGA-BRCA dataset, between HNRNPA2B1 expression and NQO1 stability." (PMID 37169843, 2023).
lung cancer (45 papers, 2010 to 2025). A malignant neoplasm involving the lung. "Hnrnpa2b1, an N6-methyladenosine (m6a) reader, can recognize pathogen DNA and mediate innate immune response, expressing highly in pan cancerous such as lung cancer, gastric cancer, and liver cancer, which is associated with poor prognosis." (PMID 38982226, 2024). "HNRNPA2B1 has also been reported to be highly expressed in lung cancer and is strongly associated with poor prognosis in lung cancer patients." (PMID 39268079, 2024). "Together, our above studies demonstrated that hnRNPA2B1 regulated the selective sorting of miR-122 into EVs through binding with the EXO-motif, and hnRNPA2B1 was tightly associated with lung cancer genesis and development." (PMID 34884671, 2021). "Next, we wondered whether hnRNPA2B1 was closely associated with the genesis and development of lung cancer." (PMID 34884671, 2021). "Since the Sp1 level is tightly regulated during lung cancer progression, understanding the molecular mechanisms underlying the regulation by Nm23-H1/hnRNPA2B1 of Sp1 expression in the various stages of lung cancer will be beneficial for lung cancer therapy in the future." (PMID 28831131, 2017). "We also observed the HnRNPA2B1 protein level was increased in clinical lung cancer samples by immunohistochemistry (IHC) staining." (PMID 40770637, 2025). "In lung cancer cells, miR-122-5p is selectively secreted into lung cancer exosomes by binding to the RNA-binding protein hnRNPA2B1." (PMID 39872394, 2024). "Overall,HNRNPA2B1 andIGF2BP3 are potential interacting genes related to the involvement of SEC61G in the progression of lung cancer, but further experimental validation is needed." (PMID 38978503, 2024). "hnRNPA2B1 was identified to distinguish early-stage lung cancer with sensitivity of 84.8% in brushing, 80.8% in biopsies and 72.2% in serum." (PMID 37716979, 2023). "HnRNPA2B1 also can be acetylated by p300, a common transcriptional coactivator, and promotes nonsmall cell lung cancer (NSCLC) growth by activating COX-2 signaling." (PMID 37546413, 2023). "Then, the top 100 HNRNPA2B1 correlation genes were selected via the GEPIA2, and we presented the connection between the top six genes and HNRNPA2B1 in pan-cancer and lung cancer." (PMID 35529270, 2022). "More importantly, hnRNPA2B1 is often upregulated by other malignancies including breast, colon, liver, and lung cancer, our findings also have broader implications for the mechanisms of bone metastasis caused by these and other tumors." (PMID 36451863, 2022). "Surprisingly, we found that inhibiting HNRNPA2B1 expression can reduce the proliferation rate of lung cancer cells." (PMID 35529270, 2022). "Several studies revealed that activated hnRNPA2B1 promotes tumor growth and malignant capability in ovarian and lung cancers." (PMID 34786210, 2021). "Because miR-122 is downregulated in lung cancer cells and upregulated in EVs derived from lung cancer, we selected hnRNPA2B1 and Rab27b, which were upregulated in lung cancer cells, as the potential research object." (PMID 34884671, 2021). "Quantitative PCR results showed that hnRNPA2B1 and Rab27b were significantly upregulated in A549 lung cancer cells." (PMID 34884671, 2021). "Here, we demonstrated that the selective sorting and secretion of tumor suppressor miR-122-5p into lung cancer EVs was regulated by RNA-binding protein hnRNPA2B1." (PMID 34884671, 2021). "These analysis with TCGA and CAPTA database showed that hnRNPA2B1 was upregulated in lung cancer patients and was negatively related to the overall survival rates of LUAD and LUSC patients." (PMID 34884671, 2021). "In this study, we found that miR-122-5p was selectively sorted and secreted into lung cancer EVs through binding to RNA-binding protein hnRNPA2B1." (PMID 34884671, 2021). "In conclusion, our studies demonstrated that RNA-binding protein hnRNPA2B1-mediated sorting and secretion of miR-122-5p into EVs promoted the progression of lung cancer." (PMID 34884671, 2021).
lung cancer (continued). "Higher-grade lung cancer samples showed a higher HnRNPA2B1 expression level." (PMID 40770637, 2025). "Moreover, the Kaplan-Meier plot analysis also revealed that lung cancer patients with higher expression of HnRNPA2B1 have a worse prognosis, including OS and RFS." (PMID 40770637, 2025). "Lastly, the TIMER database reflected the level of HNRNPA2B1 in lung cancer." (PMID 41271615, 2025). "The HNRNPA2B1 levels were positively associated with TARDBP (R = 0.83), DHX9 (R = 0.73), HNRNPR (R = 0.77), SRSF1 (R = 0.79), HNRNPD (R = 0.75), and HNRNPM (R = 0.78) genes in lung cancer (all P < 0.001)." (PMID 35529270, 2022). "HNRNPA2B1 shows high expression in lung cancers and serves as a m6A regulator." (PMID 35441574, 2022). "Furthermore, we focused on the function of hnRNPA2B1 in regulating the selective release of miR-122 into lung cancer EVs for further research." (PMID 34884671, 2021). "In addition, the analysis with survival data from TCGA database indicated that lung cancer patients with high expression of hnRNPA2B1 had lower overall survival rates." (PMID 34884671, 2021). "HNRNPA2B1 from the A/B subfamily of ubiquitously expressed heterogeneous nuclear ribonucleoproteins (hnRNPs), was identified as a biomarker for early diagnosis of lung cancer since it was overexpressed in NSCLC." (PMID 32351780, 2020). "Aberrant expression of hnRNPs in cancers have been detected, for example hnRNPA2B1 in breast, pancreatic and gastric cancer, hnRNPB1 in lung cancer, esophagus cancer, leukemia and lymphoma, hnRNPC1/C2 in lung cancer, hnRNPA2B2 in thyroid cancer and hnRNPM4 in lung cancer." (PMID 26805816, 2016). "To evaluate whether HnRNPA2B1 plays an important role in circDCP2-induced malignancy, we first initially analyzed the expression of HnRNPA2B1 in various stages of lung cancer based on the TCGA database and found that HnRNPA2B1 was upregulated in lung cancer tissues compared to normal tissues." (PMID 40770637, 2025). "In addition, our results also suggested that hnRNPA2B1-mediated secretion of EVs-miR-122-5p in lung cancer might participate potentially in the establishment of hepatic pre-metastasis niche." (PMID 34884671, 2021). "HNRNPA2B1 could interact with LINC01234 to promote lung cancer progression." (PMID 33134163, 2020). "It has been demonstrated that HNRNPA2B1-mediated m6A modification of lncRNA MEG3 facilitates tumorigenesis and metastasis of nonsmall cell lung cancer cells by regulating the miR-21-5p/PTEN axis." (PMID 39268079, 2024). "HnRNPA2B1 bound to miR-122-5p through EXO-motif, which regulated the selective secretion of miR-122-5p into lung cancer EVs." (PMID 34884671, 2021). "To evaluate the expression profile of m6A readers in lung cancer, we analyzed known readers, including YTHDF1/2/3, YTHDC1/2, HNRNPA2B1, HNRNPC/G, eIF3A, FMR1 and IGF2BP1/2, in LUAD and lung squamous cell carcinoma (LUSC) via the GEPIA database." (PMID 33232910, 2021). "Already, C1orf112 mRNA is a target gene of m6A reader, HNRNPA2B1, and methionine restriction can lead to a dramatic reduction in m6A signals in human lung cancer cells (data not shown)." (PMID 38769167, 2024). "We previously discovered that the level of HNRNPA2B1 expression is higher in pancreatic cancer than in non-lesion tissue, as are other cancers, such as lung cancer, hepatocellular carcinoma and glioblastoma." (PMID 28077929, 2017). "Previously, studies have investigated the role of thirteen m6A regulatory genes in lung cancer, but the roles of seven newly discovered ones, namely, METTL16, YTHDF3, IGF2BP1, IGF2BP2, IGF2BP3, HNRNPG, and HNRNPA2B1 has not been determined." (PMID 33795529, 2021).
amyotrophic lateral sclerosis (32 papers, 2014 to 2026). Amyotrophic lateral sclerosis (ALS) is a neurodegenerative disease characterized by progressive muscular paralysis reflecting degeneration of motor neurons in the primary motor cortex, corticospinal tracts, brainstem and spinal cord. "Interestingly, mutations of HNRNPA1 and HNRNPA2B1 are identified in families of multisystem proteinopathy or amyotrophic lateral sclerosis." (PMID 36831269, 2023). "Among them, TDP43, FUS, and hnRNPA2B1 represent molecular hallmarks of amyotrophic lateral sclerosis (ALS), where these RBPs are known for nuclear loss of function, aggregation tendency, and stress granules assembly." (PMID 40103230, 2025). "In human multisystem proteinopathy and amyotrophic lateral sclerosis (ALS), mutations in the prion-like domains of hnRNPA2B1 and hnRNPA1 occur." (PMID 32905346, 2020). "hnRNPA2B1 plays a vital role in a variety of diseases including amyotrophic lateral sclerosis, pulmonary arterial hypertension, obesity and innate immune response, particularly in cancer, where hnRNPA2B1 has been recommended as a candidate marker for cancer screening." (PMID 37716979, 2023). "Interestingly, the NiV W protein was found to interact with hnRNPA2B1, a protein known to be involved in proteinopathy and amyotrophic lateral sclerosis (ALS), to exhibit an intrinsic tendency to assemble into self-seeding fibrils and to be incorporated in stress granules." (PMID 35055108, 2022). "Additionally, some cases of PDB-like syndromes have been attributed to mutations in VCP, TNFRSF11A, TNFRSF11B, HNRNPA2B1, HNRNPA1, ZNF687 and PFN1, most of which are known to involved in the amyotrophic lateral sclerosis (ALS) and nuclear factor kappa B (NF-kB) signaling pathways." (PMID 35355568, 2022). "Mutations affecting several RBPs, including FUS, TDP-43, hnRNPA1, hnRNPA2B1, matrin-3, and TIA1, are linked to amyotrophic lateral sclerosis (ALS), frontotemporal dementia (FTD), multisystem proteinopathy (MSP), and hereditary inclusion body myopathy (hIBM) phenotypes." (PMID 34291734, 2021). "Genetic analyses of patients with amyotrophic lateral sclerosis (ALS) have revealed a strong association between mutations in genes encoding many RNA-binding proteins (RBPs), including TARDBP, FUS, hnRNPA1, hnRNPA2B1, MATR3, ATXN2, TAF15, TIA-1, and EWSR1, and disease onset/progression." (PMID 32547363, 2020).
glioma (31 papers, 2015 to 2025). A benign or malignant brain and spinal cord tumor that arises from glial cells (astrocytes, oligodendrocytes, ependymal cells). "Regarding the role of IGF2BP3 in the carcinogenicity of circNEIL3, it has been found that circNEIL3 is packaged as an exosome by hnRNPA2B1 and transferred to infiltrate tumor-associated macrophages (TAMs), thus gaining immunosuppressive properties that promote glioma progression." (PMID 38072944, 2023). "Finally, circNEIL3 could be packaged into exosomes by hnRNPA2B1 and transmitted to infiltrating glioma-associated macrophages, thereby enabling them to acquire immunosuppressive properties by stabilizing IGF2BP3, which in turn promotes glioma progression." (PMID 35031058, 2022). "The hnRNPA2B1 ablation exhibited a significant tumour-suppressive effect on glioma cell proliferation, GSC self-renewal and tumorigenesis." (PMID 40469294, 2025). "Meanwhile, we further confirmed the expression of HNRNPA2B1 in different grades of glioma cells using qRT-PCR." (PMID 39268079, 2024). "This modulation alters the expression of proteins like B-cell lymphoma-2 (Bcl-2), CyclinD1, and PCNA, underscoring the role of HNRNPA2B1 in glioma cell proliferation and its therapeutic potential." (PMID 38474421, 2024). "Combining HNRNPA2B1 suppression with cholesterol metabolism drugs yields potent inhibitory effects on glioma cells." (PMID 38474421, 2024). "For example, hnRNPA2B1 can directly bind to circNEIL3 and maintain the expression of circNEIL in exosomes, thereby delivering it to macrophages and promoting glioma development." (PMID 39584047, 2024). "HNRNPA2B1 has been reported to be highly expressed in glioma and is closely related to the poor prognosis of glioma patients." (PMID 39268079, 2024). "A similar risk signature (ALKBH5, IGF2BP2, IGF2BP3, HNRNPA2B1, YTHDF1, YTHDF2, RBM15, and WTAP) was shown to be prognostic for glioma patients, and the expression of IGF2BP2 and IGF2BP3 was linked to tumour occurrence, development, and progression." (PMID 36831575, 2023). "In the future, nanoparticles or engineered extracellular vesicles can be used to knockdown hnRNPA2B1 targeting glioma cells to block the process." (PMID 35501306, 2022). "Previous studies have shown that YTHDF1, YTHDF2, IMP2 and hnRNPA2B1 are highly expressed in gliomas, while hnRNPC is poorly expressed in gliomas." (PMID 35688823, 2022). "We knocked down hnRNPA2B1 in glioma cells and found that the exo/cell ratio of miR-1298-5p decreased." (PMID 35501306, 2022). "Glioma sorted oncosuppressor miR-1298-5p into exosomes via heterogeneous nuclear ribonucleoprotein A2B1 (hnRNPA2B1)." (PMID 35501306, 2022). "CircNEIL3 is packaged into the exosomes by hnRNPA2B1 and is delivered to TAMs from glioma cells, afflicting an immunosuppressive phenotype by stabilizing the IGF2BP3 protein, thereby promoting glioma progression." (PMID 36009578, 2022). "By enhancing the expression of the oncogenic isoforms of these genes, HNRNPA2B1 promotes glioma progression and aggressiveness." (PMID 32272554, 2020). "The RNA-binding protein, HNRNPA2B1, can regulate the splicing of many tumor suppressor genes in glioma, such as RON, BIN1, WWOX, and c-FLIP." (PMID 32272554, 2020). "hnRNPA2B1 protein is highly expressed in glioma tissues, correlated with glioma grades and related to poor prognosis." (PMID 32244981, 2020). "Although heterogeneous nuclear ribonucleoprotein A2/B1 (hnRNPA2/B1) was previously presumed to be a tumor-promoting gene, the relationship between hnRNPA2/B1 and glioma is unclear." (PMID 32463472, 2020). "By contrast, the opposite trend was observed for the HNRNPA2B1 gene, which is highly expressed in recurrent tumors compared to primary gliomas or in the latter vs. normal tissue." (PMID 31551755, 2019). "HNRNPA2B1 is identified as an independent prognostic factor for glioma." (PMID 38474421, 2024).